SATB1 (SATB homeobox 1)
Diseases named in the same sentence as SATB1 in open-access papers (continued):
Sharing a sentence is not in itself a finding about the gene and the disease.
ovarian carcinoma (8 papers, 2012 to 2025). A malignant neoplasm originating from the surface ovarian epithelium. "SATB1 knockdown in ovarian cancer cells reduces lactate dehydrogenase (LDH) and monocarboxylate transporter 1 (MCT1) expression, key mediators of glucose metabolism." (PMID 40071088, 2025). "A significant SATB1 overexpression was observed in epithelial ovarian cancer cases as compared to normal ovarian tissue." (PMID 31450715, 2019). "Despite that, in epithelial ovarian cancer SATB1′s expression was revealed to be a marker of poor prognosis." (PMID 31450715, 2019). "SATB1 was found to be overexpressed in numerous malignancies, including lymphomas, breast, colorectal, prostate, liver, bladder and ovarian cancers." (PMID 31450715, 2019). "In this study, we investigated the molecular correlates and prognostic impact of SATB1 expression in human epithelial ovarian cancer (EOC)." (PMID 22992394, 2012). "Besides the normal, physiological processes, SATB1 was found to be overexpressed in numerous malignancies, including lymphomas, breast, colorectal, prostate, liver, bladder and ovarian cancers, osteosarcoma and glioma." (PMID 31450715, 2019). "Since SATB1 expression is strongly up-regulated in various types of cancer, SATB1565–574 may serve as a diagnostic tool or an immunotherapeutic target of cancer vaccines for ovarian cancer, lymphoma and other types of cancer." (PMID 23437226, 2013). "Univariable Cox regression analysis revealed that SATB1 expression, while not prognostic in the full cohort, was associated with a reduced ovarian cancer-specific survival and 5-year overall survival in high grade tumours (n = 105) (HR = 2.14 and HR = 1.96, respectively)." (PMID 22992394, 2012). "In a recent study on epithelial ovarian cancer (EOC), SATB1 expression was found to be up-regulated both at the mRNA and protein level in EOC (n = 91) compared to borderline tumours and normal ovarian tissue." (PMID 22992394, 2012). "The results from this study demonstrate that SATB1 expression is an independent factor of poor prognosis in high grade ovarian carcinoma, regardless of histological subtype." (PMID 22992394, 2012). "Kaplan-Meier analysis and log rank test were applied to illustrate differences in ovarian cancer specific survival (OCSS) and 5-year overall survival (OS) in strata according to negative (0-1%) and positive (>1%) SATB1 expression." (PMID 22992394, 2012).
endometrial cancer (7 papers, 2017 to 2025). Primary or metastatic malignant neoplasm involving the endometrium (mucous membrane that lines the endometrial cavity). "LINC01016‐miR‐302a‐3p/miR‐3130‐3p/NFYA/SATB1 axis plays a crucial role in the occurrence of endometrial cancer." (PMID 33216456, 2021). "Collectively, these results suggested that NFYA contributed to the malignant behavior of endometrial cancer cells by directly binding to the promotor region of SATB1." (PMID 29467441, 2018). "Here, we found that LINC01016 promoted oncogenic processes by targeting miR-302a-3p and miR-3130-3p and inducing the overexpression of NFYA, thus affecting SATB1 expression in endometrial cancer cells." (PMID 29467441, 2018). "We confirmed that NFYA and SATB1 mRNA and protein were overexpressed in endometrial cancer tissues compared to normal tissues by qRT-PCR and western blotting and immunohistochemistry (IHC)." (PMID 29467441, 2018). "Given that NFYA and SATB1 were found to be overexpressed in endometrial cancer tissues, we explored the role of NFYA in malignant progression in endometrial carcinogenesis." (PMID 29467441, 2018). "The expression levels of LINC01016, miR-302a-3p, miR-3130-3p, NFYA, and SATB1 were evaluated by quantitative real-time polymerase chain reaction (qRT-PCR) in 33 endometrial cancer tissues and 20 normal tissues." (PMID 29467441, 2018). "This study was the first to show that the LINC01016–miR-302a-3p/miR-3130-3p/NFYA/SATB1 axis played a crucial role in the occurrence of endometrial cancer." (PMID 29467441, 2018). "Collectively, our results illustrated that LINC01016-miR-302a-3p/miR-3130-3p-dependent regulation modulated the expression of NFYA and SATB1 in endometrial cancer cells." (PMID 29467441, 2018). "Mir-3130 has been found to inhibit the expression of NDUFS1 to promote the invasiveness of lung adenocarcinoma in vivo and in vitro and could also regulate the miR-3130-3p/NFYA/SATB1 axis to promote the occurrence and development of endometrial cancer cells." (PMID 39591000, 2024). "The LINC01016/miR-302a-3p/miR-3130-3p/NFYA/SATB1 axis highlighted a novel class of lncRNA–miRNA interactions, which may guide future treatments in endometrial cancer." (PMID 29467441, 2018). "Hence, SATB1 was identified as a downstream gene target in LINC01016-miR-302a-3p/miR-3130-3p-NFYA regulatory axis in endometrial cancer." (PMID 29467441, 2018). "However, the specific mechanical role of SATB1 in endometrial cancer remains ambiguous." (PMID 29467441, 2018). "LINC01016 and miR-302a-3p/miR-3130-3p made up two bidirectional regulatory feedback loops that mediated the malignant phenotype of endometrial cancer cells via NFYA and its target SATB1." (PMID 29467441, 2018). "With a high expression level in endometrial cancer tissues, NFYA directly targeted the promotor region of SATB1 and contributed to the transcription of SATB1." (PMID 29467441, 2018). "Additionally, SATB1 has been identified as an independent negative prognostic marker in patients with endometrial cancer." (PMID 40071088, 2025).
lymphoma (7 papers, 2013 to 2024). A malignant (clonal) proliferation of B- lymphocytes or T- lymphocytes which involves the lymph nodes, bone marrow and/or extranodal sites. "As the authors could not indicate the significance of mutated SATB1 and its expression in high-grade nodal lymphomas in dogs, further study is required to confirm the significant pathogenesis, and a target drug that could restore SATB1 function might be helpful for the treatment of canine lymphomas." (PMID 35332215, 2022). "Taken together, the currently available literature on the roles of SATB1 and p16 in lymphoma provides contradictory data." (PMID 39195213, 2024). "Contrary to observations in solid tumors, SATB1 appears to suppress the progression of leukemia and lymphoma." (PMID 31130823, 2019). "Given that SATB1 levels are dysregulated in various cancers, including lymphoma, with a further link to PD‐1 regulation, our study can be of relevance to anti‐PD‐1 immunotherapies in cancer clinical trials." (PMID 30803026, 2019). "Our previous study showed that SATB1 expression was decreased in T cell leukemia/lymphoma." (PMID 31130823, 2019). "The expression of SATB1 in lymphoma remains unclear and contradictory." (PMID 39195213, 2024).
Autoimmunity (6 papers, 2013 to 2022). The occurrence of an immune reaction against the organism's own cells or tissues. "Satb1 is crucial for Treg cell super-enhancer establishment and thus for the induction of Treg cell signature genes, and developmental stage-specific deletion of Satb1 leads to autoimmunity due to Treg cell deficiency." (PMID 36569861, 2022). "Nevertheless, the risk of autoimmunity induced by SATB1-targeted immunotherapy should be still considered in future clinic trials and impact of SATB1-specific T cells on developing T cells in vivo needs further exploration." (PMID 23437226, 2013). "Satb1-deficient mice suffer from multiple health problems, markedly resembling autoimmunity." (PMID 36376298, 2022). "A great example for a cell-intrinsic mechanism of autoimmunity in the Satb1 cKO is the SATB1-dependent spatial rearrangement of the TCRα enhancer and the TCR locus per se, controlling TCR recombination." (PMID 36376298, 2022). "SATB1 in turn is predominantly expressed in CD4 + CD8 + lymphocytes exerting both activating and repressive regulatory functions implicated in autoimmunity and cancer." (PMID 34785669, 2021). "The genome organizer SATB1, which is highly expressed during most stages of T cell thymic selection, was recently involved in setting-up thymic-derived Treg cell functional features and ability to prevent autoimmunity before Foxp3 is turned on27." (PMID 30560927, 2018). "In addition, mice without SATB1 in their T cells failed to respond to antigens, albeit SATB1-deficient mice are prone to developing autoimmune disorders." (PMID 34583974, 2021). "Thus, the difference in SATB1 expression on normal and malignant cells may explain the reason that SATB1-specific T cells in healthy donors do not cause autoimmunity, SATB1-targeted immunotherapy is expected to be safe to treat cancer patients." (PMID 23437226, 2013).
bladder cancer (6 papers, 2013 to 2024). "SATB1 expression was increased significantly in bladder cancer cell lines as compared to normal bladder cell lines." (PMID 37627900, 2023). "The knockdown of SATB1 in two high-grade bladder cancer cell lines (TCCSUP and 5637) showed opposite functional roles." (PMID 37627900, 2023). "Higher SATB1 expression was found in stage T2–T4 tumors when compared to stage T1 tumors, thus suggesting that SATB1 plays an important role in bladder cancer progression." (PMID 37627900, 2023). "The overexpression of SATB1 was noticed also in urinary bladder cancer cell lines and clinical samples." (PMID 31450715, 2019). "In addition, SATB1 expression was to be a significant and independent prognostic factor for bladder cancer." (PMID 37627900, 2023). "Additionally, an analysis of the loss-of-function and gain-of-function models revealed the influence of SATB1′s expression on bladder cancer cell proliferation, migration, apoptosis and sensitivity to cisplatin-based chemotherapy." (PMID 31450715, 2019). "The fact that SATB1′s overexpression was shown to be associated with the shorter survival of bladder cancer patients was not a surprise." (PMID 31450715, 2019). "Therefore, SATB1 may be a therapeutic target for bladder cancer." (PMID 37627900, 2023). "Both the mRNA and protein expression of SATB1 and ERBB2 were significantly upregulated in bladder cancer tissues when compared to normal bladder tissues." (PMID 37627900, 2023). "SATB1 was also highly expressed in bladder cancer 5637 and T24 cells but was not expressed in the SV-HUC-1 cells." (PMID 37627900, 2023). "SATB1 expression was detected in 38.8% of FFPE bladder cancer tissues but was not expressed in normal bladder tissues." (PMID 37627900, 2023). "The same trend was observed in which the SATB1 expression level was higher in the metastatic bladder cancer T24 cells than in the non-metastatic bladder cancer BIU-87 cells." (PMID 37627900, 2023).
lung adenocarcinoma (6 papers, 2020 to 2025). A carcinoma that arises from the lung and is characterized by the presence of malignant glandular epithelial cells. "Additionally, we constructed a RP11-2B6.2-miR-149-5p-/RP11-67L2.2-miR-330-3p-SYNE3 ceRNA network and a SATB1-miR-149-5p-SYNE3 transcriptional network in lung adenocarcinoma to support the tumor-suppressing role of SYNE3." (PMID 32948197, 2020). "For instance, in lung adenocarcinoma, HDAC5-mediated deacetylation of SATB1 can also affect its transcriptional regulatory activity on downstream genes." (PMID 40781327, 2025). "For instance, we found positive correlations between SOX9 and SATB1 with these markers in colon adenocarcinoma (COAD) and lung adenocarcinoma (LUAD), respectively." (PMID 35201514, 2021).
osteosarcoma (6 papers, 2017 to 2025). A usually aggressive malignant bone-forming mesenchymal neoplasm, predominantly affecting adolescents and young adults. "Conversely, miR-23a acts as a tumor suppressor in osteosarcoma by inhibiting SATB1 expression, reducing SATB1 mRNA and protein levels and suppressing cell proliferation." (PMID 40071088, 2025). "Runx1 and Ikzf1 have been shown to be targets of mirn23a miRNAs in hematopoietic cells, and Satb1 was shown to be a direct target in osteosarcoma cells." (PMID 28704388, 2017). "For example, increasing the level of one or more SATB1-specific miRNAs in osteosarcoma might improve the response to vincristine." (PMID 30576489, 2018).
esophageal cancer (5 papers, 2014 to 2025). A primary or metastatic malignant neoplasm involving the esophagus. "SATB1 has been closely linked to the progression of esophageal cancer, particularly esophageal squamous cell carcinoma (ESCC), the most common form of esophageal cancer, arising primarily from abnormal squamous epithelial cell proliferation." (PMID 40071088, 2025). "In this study, we performed a systematic review of literatures and meta-analysis to determine the association between SATB1 expression and overall survival (OS) in colorectal, gastric and esophageal cancer." (PMID 28430598, 2017). "To explore the molecular function of SATB1 in esophageal cancer, we evaluated the cell viability using MTT assay." (PMID 28147311, 2017). "Our MTT results showed that the knockdown of SATB1 in highly expressed esophageal cancer cells diminished their proliferation and survival from 48 h to 72 h." (PMID 28147311, 2017). "As far as we know, this is the first molecular evidence suggesting the SATB1 function in promotion of esophageal cancer cell proliferation and survival." (PMID 28147311, 2017). "Our results illustrated the unique functional regulatory role of SATB1 for the esophageal cancer whole genomic transcriptome." (PMID 28147311, 2017). "The present study was carried out to explore the function of SATB1 in the development of human esophagus cancer." (PMID 28147311, 2017). "The endogenous expression level of SATB1 was first checked in two esophageal cancer cell lines, TE-1 and EC109." (PMID 28147311, 2017). "In conclusion, SATB1 is an oncogenic gene involved in esophageal cancer tumor cell proliferation and metastatic potential regulation; its function is partially delivered by the downstream genes FN1 and PDGFRB." (PMID 28147311, 2017). "Network analysis and functional experiments further identified FN1 and PDGFRB to be key downstream genes regulated by SATB1 in esophageal cancer cells." (PMID 28147311, 2017). "In summary, we provided the first molecular evidence that SATB1 played an oncogenic role in esophageal cancer by up-regulation of FN1 and PDGFRB." (PMID 28147311, 2017). "Here we showed that the knockdown of SATB1 in esophageal cancer cell lines diminished the cell proliferation, survival and invasion." (PMID 28147311, 2017). "Given the strong clinical relevance of SATB1 in esophagus cancer and other cancers suggested by previous studies, the exact function of SATB1 in esophagus cancer development is still unknown." (PMID 28147311, 2017). "Understanding the function of SATB1 in esophageal cancer could have potential implication for diagnosis and therapy." (PMID 28147311, 2017). "Given the strong clinical relevance, the exact function of SATB1 in esophagus cancer development is still unknown." (PMID 28147311, 2017). "Thus, SATB1 is a promising therapeutic target and prognostic marker in esophageal cancer." (PMID 40071088, 2025). "SATB1 might serve as a therapeutic target and prognostic marker for esophageal cancer." (PMID 28147311, 2017). "The prognostic value of SATB1 expression in esophageal cancer has, however, not yet been described." (PMID 25326863, 2014). "SATB1 expression has, to our best knowledge, not been examined in esophageal cancer." (PMID 25326863, 2014).
lung squamous cell carcinoma (5 papers, 2012 to 2024). "However, certain studies have also demonstrated low levels of SATB1 in non-small cell lung tumors with a proven unfavorable forecast in lung squamous cell carcinomas." (PMID 39195213, 2024).
nasopharyngeal carcinoma (5 papers, 2013 to 2022). A carcinoma arising from the nasopharyngeal epithelium. "In nasopharyngeal carcinoma studies, it was found that DRAIC can sponge miR-122 to promote the expression of SATB1, thus promoting the proliferation, migration, and invasion of nasopharyngeal carcinoma cells." (PMID 34306024, 2021). "In nasopharyngeal carcinoma cells, lncRNA DRAIC boosted cell migration and invasion through its interaction with miR-122 and the consequent increase of SATB1 levels." (PMID 35992823, 2022). "Functional assays revealed that DRAIC acts as a miR-122 sponge to facilitate nasopharyngeal carcinoma cell proliferation, migration, and invasion via regulating SATB homeobox 1 (SATB1)." (PMID 34471485, 2021). "However, the role of SATB1 in human nasopharyngeal carcinoma (NPC) remains unknown." (PMID 24047082, 2013). "Whether SATB1 involves radiation resistance in nasopharyngeal carcinoma (NPC) and underlying mechanism of SATB1 to participate in chemoradiotherapy resistance in NPC have not been elaborated." (PMID 33390772, 2021).
autoimmune disease (4 papers, 2019 to 2022). A disorder resulting from loss of function or tissue destruction of an organ or multiple organs, arising from humoral or cellular immune responses of the individual to their own tissue constituents. "When assessing SATB1’s function in autoimmune disorders, a good model of investigation is the induction of experimental autoimmune encephalitis (EAE) in mice." (PMID 35812421, 2022). "Multiple SATB1 perturbations in mice uncovered a link to autoimmune diseases while clinical investigations on cancer research uncovered that SATB1 has a promoting role in several types of cancer and can be used as a prognostic biomarker." (PMID 33356851, 2020). "Satb1-mediated regulation of Bhlhe40 and PD-1 controls Th17 pathogenicity in part by IL-17 and GM-CSF production in the central nervous system during autoimmune disease." (PMID 30710091, 2019). "Deregulation in SATB1 expression has been observed in multiple T cell derived autoimmune diseases." (PMID 35812421, 2022). "Whether such a mechanism exists in humans remains to be elucidated, which would render SATB1 protein as a prognostic marker for early detection of autoimmune diseases." (PMID 33356851, 2020). "Together, our findings, in addition to providing novel insights into the molecular mechanisms underlying the pathogenic program of tissue Th17 cells in mice, may help design novel immunotherapeutic approaches such as small molecule modifiers of Satb1 for the treatment of autoimmune diseases." (PMID 30710091, 2019).
developmental delay (4 papers, 2022 to 2025). "The special AT-rich sequence binding protein 1 (SATB1) has been linked to neurodevelopmental disorders (NDDs) including developmental delay, intellectual disabilities (ID) and autism spectrum disorder (ASD)." (PMID 40571781, 2025). "SATB1 variants causing developmental delay with dysmorphic facies and dental anomalies have been reported in a small cohort." (PMID 36120649, 2022). "Here, we present a Chinese patient with a de novo truncating variation in SATB1 who presented with mild developmental delay." (PMID 36120649, 2022). "SATB1 (MIM #602075) is a relatively new gene reported only in recent years in association with neurodevelopmental disorders characterized by variable facial dysmorphisms, global developmental delay, poor or absent speech, altered electroencephalogram (EEG), and brain abnormalities on imaging." (PMID 38790177, 2024).
esophageal squamous cell carcinoma (4 papers, 2017 to 2025). Esophageal squamous cell carcinoma (ESCC) is a type of esophageal carcinoma (EC) that can affect any part of the esophagus, but is usually located in the upper or middle third. "Conversely, SATB1 has been shown in association with esophageal squamous cell carcinomas through an overexpression." (PMID 38886487, 2024). "Wang indicated that SATB1 could significantly promote cell migration and invasion in esophageal squamous cell carcinoma." (PMID 28636989, 2017).